SIRT1 (sirtuin 1)
Diseases named in the same sentence as SIRT1 in open-access papers (continued):
Sharing a sentence is not in itself a finding about the gene and the disease.
heart failure (continued). "We hypothesized that SIRT1 was the major factor in the reduced α-MHC K1897 lactylation during heart failure, which may elevate SIRT1 expression and the binding of α-MHC to SIRT1." (PMID 37443257, 2023). "Further, our finding that SIRT1 agonist (SRT1720) restricted the ROS and oxidative stress markers (3NT and 4HNE) that otherwise were significantly induced by T. cruzi infection suggest that SIRT1/NFκB axis coordinates the oxidative stress as well as inflammation in chronic CCM and heart failure." (PMID 27764247, 2016). "Interestingly, SIRT1 expression and activity were decreased during experimental heart failure, and PARP inhibition with 3AB induced restoration of SIRT1 expression." (PMID 24586272, 2014). "We also found that, although captopril could repair mitochondrial damage in myocardial cells of rats with heart failure, it did not affect the protein and mRNA levels of SIRT1, p-AMPK, and PGC-1α." (PMID 37089931, 2023). "Our result suggests that the AMPK-Nampt-Sirt1 pathway may be disordered in heart failure and the mechanism of aging and heart failure is similar but not exactly the same." (PMID 24913149, 2014). "However, expression of Sirt1 in advanced heart failure models is not clear and remains controversial." (PMID 24913149, 2014). "For instance, studies have shown that doxorubicin inhibits SIRT1 and AMPK in the hearts of male Wistar rats and cultured cells, suggesting that the restoration of these two pathways may be of benefit in doxorubicin-induced heart failure." (PMID 25237749, 2014). "The role of Sirt1 in heart failure, especially in human hearts is not clear." (PMID 24913149, 2014). "In light of the universal nature of down-regulation of SERCA2a protein/mRNA and its dysfunction in heart failure, whether activation of SIRT1 ameliorates heart failure irrespective of the etiology warrants investigation." (PMID 22622703, 2012). "However, SIRT1 is not essential in mediating α-MHC K1897 delactylation in heart failure." (PMID 37443257, 2023). "Therefore, SIRT1 may not be the core factor in decreased α-MHC K1897 lactylation during heart failure." (PMID 37443257, 2023).
ovarian carcinoma (87 papers, 2010 to 2026). A malignant neoplasm originating from the surface ovarian epithelium. "Increased expression of RXRα and Sirt1 was associated with increased survival rates in advanced stages of ovarian cancer." (PMID 34870752, 2022). "RSV, which induces apoptosis and decreases proliferation in human ovarian cancer cell lines, was associated with decreased expression of Sirt1 in mucinous ovarian cancer and increased expression of RXRα in mucinous, carboplatin resistant ovarian cancer cells." (PMID 34870752, 2022). "Our report shows that the expression of nuclear RXRα and Sirt1 in advanced ovarian cancer is significantly associated with longer overall survival." (PMID 34870752, 2022). "The authors emphasize the special role of nuclear SIRT1 as a potential biomarker of endometriosis and ovarian cancer associated with endometriosis." (PMID 33435147, 2021). "The conclusions of their research indicate a significant role of KRAS and SIRT1 in the pathogenesis of endometriosis as well as ovarian cancer associated with endometriosis." (PMID 33435147, 2021). "We elucidated that up-regulation of miR-142 in ovarian cancer promoted Th1 differentiation to induce tumor cell apoptosis via controlling Sirt1, which was closely associated with cell growth, proliferation, differentiation, and apoptosis." (PMID 31038546, 2019). "Downregulation of SIRT1 also led to decreased migration and angiogenesis of ovarian cancer cells by repressing HMGB1, and was associated with decreased OS in serous ovarian cancer." (PMID 31113446, 2019). "SIRT1 overexpression is reported by many authors as associated with poor outcome and chemoresistance in ovarian cancer of epithelial origin." (PMID 30319549, 2018). "Hereditary breast and ovarian cancer susceptibility gene product BRCA1 has been shown to serve as a positive regulator of SIRT1 expression by binding to the promoter region of SIRT1, but cross talk between BRCA1 and TFII-I has not been investigated to date." (PMID 21407215, 2011). "Additionally, nuclear expression of RXRα and SIRT1 in advanced ovarian cancer was associated with improved overall survival." (PMID 41471349, 2025). "High expression of SIRT1 in ovarian cancer cells promotes the migration, proliferation, and differentiation of cancer cells and it is highly associated with cisplatin resistance and poor prognosis in ovarian cancer patients." (PMID 36975503, 2023). "In ovarian cancer cells, loss of SIRT1 mRNA expression is associated with higher expression of ERβ." (PMID 36235125, 2022). "In contrast, an overexpression of Sirt1 in ovarian cancer is associated with poor prognosis." (PMID 34870752, 2022). "However, in contrast, other studies showed that SIRT1 overexpression or activation resulted in acquired chemoresistance and increased invasiveness of ovarian cancer cells, and was associated with a poorer prognosis in serous ovarian cancer patients." (PMID 31113446, 2019). "SIRT1 is also implicated in LPA (lysophosphatidic acid)-induced EMT in ovarian cancer cells." (PMID 30064416, 2018). "Previous study demonstrated that SIRT1 overexpression is associated with poor outcome and chemo-resistance in ovarian cancer of epithelial origin over-expression, and one of the mechanisms may involve the dysregulation of energy metabolism and stress response 16,18." (PMID 32398958, 2020). "Knocking down SIRT1 can inhibit the proliferation, invasion and migration of ovarian cancer cells, promote cell apoptosis, and reduce the drug resistance of cells to cisplatin." (PMID 41858354, 2026). "SIRT1 enhances the malignant biological behavior of ovarian cancer cells by promoting glycolysis and angiogenesis." (PMID 41858354, 2026). "In certain settings, SIRT1 suppresses ovarian cancer depending on its subcellular localization and counters tumor growth." (PMID 41300302, 2025).
ovarian carcinoma (continued). "Research found that puerarin, a natural isoflavone, induces apoptosis in platinum-resistant epithelial ovarian cancer cells by targeting SIRT1." (PMID 41300302, 2025). "Another study reported that SIRT1 overexpression contributed to paclitaxel resistance in ovarian cancer cells." (PMID 41471349, 2025). "In ovarian cancer, SIRT1 facilitates the cellular adaptation to oxidative stress by modulating key redox-sensitive transcription factors." (PMID 41008982, 2025). "Inhibition of SIRT1 sensitizes ovarian cancer cells to cisplatin and paclitaxel by reactivating apoptosis pathways." (PMID 41300302, 2025). "SIRT1 was observed to also deacetylate certain tumor activation factors such as Claudin 5, which resulted in suppressing ovarian cancer." (PMID 41300302, 2025). "In ovarian cancer, SIRT1’s deacetylation activity can promote cell survival, proliferation, and metastasis, which contributes to cancer progression." (PMID 41300302, 2025). "In ovarian cancer, SIRT1 is often overexpressed, contributing to tumorigenesis, metastasis, and resistance to chemotherapy." (PMID 41300302, 2025). "MHY2245 was shown to inhibit SIRT1 activity, induce autophagy, and promote apoptosis in human ovarian cancer cells." (PMID 41300302, 2025). "Reduced SIRT1 expression attenuated ROS production in H2O2-treated epithelial ovarian cancer cells, attributed to negative regulation of SIRT1 targeting by miR-29b." (PMID 40028033, 2025). "As in the other cancers discussed thus far, SIRT1 plays a multifaceted role in tumor progression, metastasis, and drug resistance in ovarian cancer." (PMID 41300302, 2025). "At present, only two studies have suggested that there exists a close relationship between cytoplasmic SIRT1 and the progression of ovarian carcinoma and squamous cell carcinoma (SCC)." (PMID 39858444, 2025). "This study suggests that MHY2245 has a potent activity against SIRT1 and holds promise for ovarian cancer therapy." (PMID 39272943, 2024). "Artesunate upregulated miRNA-142, which suppressed Sirtuin 1 (Sirt1) levels and eventually promoted Th1 differentiation—such actions led to ovarian cancer cell apoptosis." (PMID 39195233, 2024). "A recent study explored the role of the novel SIRT1 inhibitor MHY2245 in regulating apoptosis and autophagic cell death in ovarian cancer cells, along with its underlying mechanisms." (PMID 39272943, 2024). "In particular, 15-deoxy-Δ12,14-prostaglandin J2 (15d-PGJ2) exhibits potent anticancer activity by inhibiting SIRT1, and it has been found that its derivatives (J11-C1 and J19) exhibit anticancer activity against ovarian cancer SKOV3 cells in ovarian tissues." (PMID 36975503, 2023). "In an ovarian cancer model, artesunate, a medication used to treat malaria, induced Th1 cell differentiation from CD4+ T cells and showed enhanced proapoptotic effects on ovarian cancer cells by upregulating miR-142 and suppressing SIRT1 levels." (PMID 38116009, 2023). "SIRT1 over-expression decreases the expression and acetylation of high-motility group box-1 protein, thus inhibiting ovarian cancer migration, invasion and angiogenesis." (PMID 37894746, 2023). "As Sirt1 is described to induce chemo-resistance and to be associated with poor prognosis in ovarian cancer, we intended to analyze treatment with RSV in regard to Sirt1." (PMID 34870752, 2022).
ovarian carcinoma (continued). "In the present study, we immunohistochemically examined the expression of RXRα and Sirt1 in mucinous and serous ovarian cancer and analyzed the relationship between RSV, RXRα and Sirt1 in ovarian cancer in vitro." (PMID 34870752, 2022). "In conclusion, we observed that the combination of nucleus RXRα and Sirt1 expression was correlated with increased overall survival in late-stage ovarian cancer." (PMID 34870752, 2022). "Ovarian cancer has been related with CA-125 and metabolic reprogramming by SIRT1 leading to metastasis with the involvement of exosomes." (PMID 35496046, 2022). "Sirt1 and RXRα expression was analyzed in 123 cases of ovarian cancer (110 serous and 13 mucinous cases)." (PMID 34870752, 2022). "SIRT1 has been reported to contain two nuclear localization signals and two nuclear export signals, which enable it to shuttle between the nucleus and cytoplasm, and cytoplasmic SIRT1 inhibits cell migration and invasion in ovarian carcinoma." (PMID 35962432, 2022). "This miR targets Sirtuin 1 (SIRT1) and represses the proliferation and chemoresistance in ovarian cancer and targets the Wiskott–Aldrich syndrome-like protein (WASL), Integrin Alpha V, and other cytoskeletal components." (PMID 35681531, 2022). "They found that as a downstream target gene of HIF-1α, SIRT1 was involved in the promotion of cancer stem cell-like features in ovarian cancer cells by hypoxia." (PMID 33435147, 2021). "LncRNA HOTAIR can facilitate the expression of Homeobox A7 (HOXA7) and sponge miR-138-5p to rescue EZH2 and sirtuin 1 (SIRT1) expression in ovarian cancer, both of which contribute to cisplatin resistance." (PMID 34660304, 2021). "And one study about ovarian cancer concluded that microRNA-494 is a potential prognostic marker and inhibits cellular proliferation, migration and invasion by targeting SIRT1." (PMID 34820170, 2021). "One study showed that miR-506-3p suppressed proliferation and stimulated apoptosis via regulation of the Sirtuin 1 (SIRT1)/Akt/FOXO3a pathway in ovarian cancer cells." (PMID 33621206, 2021). "Here, we investigated the functional role of the novel SIRT1 inhibitor MHY2245 on the regulation of apoptosis and autophagic cell death in ovarian cancer cells, as well as its associated mechanisms." (PMID 32398958, 2020). "Further studies are necessary to elucidate the role of SIRT1 in uterine and ovarian cancer and its potential as a therapeutic target." (PMID 32388637, 2020). "In particular, over-expression of SIRT1 is correlated with lymph node metastasis and the decrease of the 5-year survival rate, indicating its oncogenic effects in ovarian cancer 40,42." (PMID 32398958, 2020). "On the other hand, Sirt1 suppresses migration and invasion in oral squamous cell carcinoma, lung and ovarian cancer." (PMID 32727075, 2020). "In some cancer types (e.g., glioma, bladder, or ovarian cancer) lower expression levels of Sirt1 have been detected, although in most cancer types an increased expression was observed." (PMID 32426286, 2020). "We showed that down-regulation of SIRT1 caused a significant reduction in phosphorylated Akt expression, and SIRT1 directly interacted with Akt in ovarian cancer cells." (PMID 32398958, 2020). "In this study, we suggest that a synthetic SIRT inhibitor represents a potential for ovarian cancer therapy that has a strong inhibitory activity on SIRT1." (PMID 32398958, 2020). "Consistent with this, some tumors including glioma, bladder and ovarian cancer show a low level of SIRT1." (PMID 32727075, 2020). "SIRT1 is over-expressed in a majority of ovarian cancers 13,14, implying a role of SIRTs in ovarian tumorigenesis." (PMID 32398958, 2020). "Specifically, in lung and ovarian cancers, SIRT1 was shown to repress EMT via cell migration inhibition." (PMID 32340156, 2020).
ovarian carcinoma (continued). "Previous study has reported that high level of Sirt1 was correlated with ovarian cancer tumorigenesis, and over-expression of Sirt1 in epithelial ovarian cancer contributed to chemoresistance and indicated poor prognosis." (PMID 31038546, 2019). "In summary, for the first time, our study showed the possible close relationship between the subcellular location of SIRT1 and the progression of ovarian carcinoma." (PMID 31317367, 2019). "Artesunate enhanced the pro-apoptotic effects of Th1 cells on ovarian cancer via the miR-142/Sirt1 pathway." (PMID 31038546, 2019). "In conclusion, the findings of this study illustrated that artesunate promotes Th1 differentiation from CD4+ T cells by down-regulating Sirt1 through miR-142, thereby enhancing cell apoptosis in ovarian cancer." (PMID 31038546, 2019). "This study initially combined the functions of Sirt1 in regulating ovarian cancer progression and Th1 differentiation, underscoring that down-regulation of Sirt1 contributed to Th1 differentiation and subsequent ovarian cancer cell apoptosis." (PMID 31038546, 2019). "In ovarian cancer, hypoxia induces the transcriptional repression of SIRT1, which contributes to EMT and enhances cancer metastasis." (PMID 31068761, 2019). "Artesunate promoted Th1 differentiation from CD4+ T cells by down-regulating Sirt1 through miR-142, thereby enhancing cell apoptosis in ovarian cancer." (PMID 31038546, 2019). "Ovarian cancer cell resistance to platinum-based drugs is largely attributed to increased SIRT1 expression." (PMID 30064416, 2018). "SIRT1 regulates EMT in ovarian cancer cells, crucial in ALS-induced autophagy, antagonizing hypoxia-induced EMT." (PMID 30064416, 2018). "We studied the dependence of ERβ function on the presence of KDM6B and SIRT1 in human ovarian cancer cells in vitro." (PMID 29422491, 2018). "Our research demonstrated that high level of HIF-1α and SIRT1 was related to the characteristics of CSCs in ovarian cancer." (PMID 28878214, 2017). "Here we provided the evidence that HIF-1α and its downstream target gene SIRT1 played an important role in the promotion of CSCs-like properties in ovarian cancer cells." (PMID 28878214, 2017). "In our work, we found that SIRT1 was overexpressed in ovarian cancer cells exposure to hypoxia condition, and its expression was regulated by HIF-1α." (PMID 28878214, 2017). "In this context, the inhibition of SIRT1 is becoming a novel approach for new treatment strategies of ovarian cancer." (PMID 28878214, 2017). "To examine the role of SIRT1 in human cancer progression, we checked the relationship between SIRT1 expression and survival of patients with ovarian cancer." (PMID 26992208, 2016). "Of human tumors, SIRT1 expression in stromal fibroblasts was found to correlate with poor prognosis in ovarian cancer." (PMID 26992208, 2016). "The growth rates of both ovarian cancer cells were raised by co-culture of SIRT1-overexpressing CCD18Lu cells, whereas they were decreased by intracellularly overexpressed SIRT." (PMID 26992208, 2016). "Although the expression of SIRT1 was higher in ovarian carcinomas compared with benign and borderline ovarian tumors, SIRT1 expression was associated favorable prognosis of ovarian carcinoma patients." (PMID 25823848, 2015). "SIRT1 expression is decreased in many other types of cancers, including human bladder, glioblastoma, and ovarian cancer compared to corresponding normal tissues." (PMID 25522783, 2014). "Hereditary breast and ovarian cancer susceptibility gene product BRCA1, by binding to the promoter region of SIRT1, is a positive regulator of SIRT1 expression." (PMID 20160719, 2010). "SIRT1 is expected to be a new target for ovarian cancer treatment." (PMID 41858354, 2026).